PBRM1 (polybromo 1)
Diseases named in the same sentence as PBRM1 in open-access papers (continued):
Sharing a sentence is not in itself a finding about the gene and the disease.
bladder cancer (continued). "Collectively, both in vitro and in vivo studies supported a growth inhibitory effect of PBRM1 on bladder cancer cells." (PMID 25978027, 2015). "We suggested that reduced expression of PBRM1 induces cell cycle arrest, in turn inhibits cell proliferation and suppresses the development of bladder cancer." (PMID 25978027, 2015). "We amplified PBRM1 genome DNA by PCR and then sequenced it in 31 paired bladder cancer tissues." (PMID 25978027, 2015). "PBRM1 significantly repressed the expression of cyclin B1 in bladder cancer cells." (PMID 25978027, 2015). "Our results demonstrated that reduced expression of PBRM1 was a central feature of bladder cancer." (PMID 25978027, 2015). "Taken together, this report indicated that PBRM1 exerted a tumor suppressing role and induced cell cycle arrest in bladder cancer, which might partly be due to suppressing cyclin B1." (PMID 25978027, 2015). "In this study, we aimed to elucidate the pathophysiological role of PBRM1 in bladder cancer." (PMID 25978027, 2015). "Notably, PBRM1 is located at chromosome 3p21, a region where structural abnormalities were also detected in bladder cancers, implying a potential tumor-suppressive function of this gene." (PMID 25978027, 2015). "However, little is known about the biological function of PBRM1 in the development or progression of bladder cancer." (PMID 25978027, 2015). "However, biological functions and prognostic values of PBRM1 in bladder cancer remain largely unexplored." (PMID 25978027, 2015). "PBRM1 suppressed bladder cancer cell growth in vitro and tumorigenicity in vivo." (PMID 25978027, 2015). "This might suggest that mutation of PBRM1 was not a possible contributing pathogenesis of bladder cancer." (PMID 25978027, 2015). "We up-regulated PBRM1 expression by transfecting pBABE-PBRM1 or pBABE-puro in UMUC-3, EJ and 5637 bladder cancer cells." (PMID 25978027, 2015). "In this report, we found that PBRM1 was down-regulated in bladder cancer cell lines and tissues compared to normal cell line and normal tissue." (PMID 25978027, 2015). "We found that mRNA and protein expression of PBRM1 was lower in the bladder cancer cell lines compared with normal uroepithelial cell line." (PMID 25978027, 2015). "Consistent with the qRT-PCR findings, PBRM1 had the highest expression in normal uroepithelium, and the expression decreased in superficial non-muscle-invasive and muscle-invasive bladder cancer tissues." (PMID 25978027, 2015).
endometrial cancer (4 papers, 2020 to 2024). Primary or metastatic malignant neoplasm involving the endometrium (mucous membrane that lines the endometrial cavity). "Endometrial cancer cDNA array analysis showed that E27 inclusion in PBRM1 was significantly higher in cancer tissues than in normal tissues." (PMID 39375538, 2024). "Similarly, more CD4+ T cells and CD8+ T cells were also observed in the POL&PBRM1 group in endometrial cancer." (PMID 39218995, 2024).
gallbladder cancer (4 papers, 2019 to 2023). "PBRM1 mutations were identified in 8.1% (n = 150) of BTCs and were more prevalent in intrahepatic BTCs (9.9%) compared to gallbladder cancers (6.0%) or extrahepatic BTCs (4.5%)." (PMID 37400502, 2023). "PBRM1 mutation frequencies were detected at the highest frequencies in intrahepatic BTC (9.9%, n = 103/1045; IHBCs) followed by gallbladder cancer (6.0%, n = 29/484) and extrahepatic BTC (4.5%, n = 11/244, EHBCs)." (PMID 37400502, 2023). "Comparing ICC with gall bladder cancer, ICC has significantly higher IDH1 (14.5%), BAP1 (9.5%), and PBRM1 (7.5%) mutation rates." (PMID 38203635, 2023).
major depressive disorder (4 papers, 2013 to 2025). An episode of depression lasting two or more weeks without an intervening episode of mania. "The SNP rs2251219, which maps to the PBRM1 locus, was originally reported in a meta-analysis of BD and major depressive disorders in a Caucasian population (P = 1.7×10−9)." (PMID 23967141, 2013).
Papillary Meningioma (4 papers, 2021 to 2023). A WHO grade III meningioma characterized by the predominance of a perivascular pseudopapillary pattern. "In addition, mutations of the PBRM1 gene, which are predominantly found in papillary meningiomas, have been also reported in single RM cases." (PMID 36674634, 2023). "In addition, there was one study that observed mutations in polybromo-1 (PBRM1) in both rhabdoid meningioma and papillary meningioma cases." (PMID 37173979, 2023). "In papillary meningiomas, the biallelic inactivation of polybromo 1 (PBRM1) gene has been described, which can overlap with BAP1 mutations, but its role is not yet understood." (PMID 34679551, 2021). "Likewise, BAP1 gene mutations and/or deletions, which are typically found in RM, have also been reported in papillary meningiomas in combination with alterations of the PBRM1 gene." (PMID 36674634, 2023).
diabetes (3 papers, 2017 to 2023). "The obesity SNP rs2710323, together with two diabetes SNPs, rs2590838 (r2, 0.78) and rs1108842 (r2, 0.8), are located in loci that regulate genes (TMEM110, MUSTN1, ITIH4, NEK4, GNL3, PBRM1, and NT5DC2) within a 300 kb genomic region on chromosome 3." (PMID 29081791, 2017).
kidney tumor (3 papers, 2018 to 2024). "Only after combination with Pbrm1 or Bap1 conditional knockout can Vhl loss lead to kidney tumors." (PMID 30355451, 2018). "Indeed, although combined deletion of Vhl and Pbrm1 results in multifocal clear cell kidney cancers indicating that Setd2 inactivation is not required for kidney tumor initiation, tumors did not metastasize in this model and loss of SETD2 may be an essential step in this process." (PMID 37418588, 2024).
metastatic tumor (3 papers, 2017 to 2022). "Lastly, we evaluated the concordance of loss of BAP1 and PBRM1 expression across patient-matched primary and metastatic tumors in a large cohort of ccRCC patients." (PMID 28327121, 2017). "We observed high concordance of loss of PBRM1 expression between patient-matched primary and metastatic tumors." (PMID 28327121, 2017). "We analyzed BAP1 and PBRM1 loss of protein expression in patient-matched primary and metastatic tumors from 97 patients." (PMID 28327121, 2017). "Patients with discordant BAP1 or PBRM1 expression across their matched primary and metastatic tumors usually showed loss of expression during progression to metastatic ccRCC." (PMID 28327121, 2017). "Of the 10 patients that demonstrated discordance, 70% had primary tumors that were IHC positive and subsequently the metastatic tumors demonstrated PBRM1 loss of expression." (PMID 28327121, 2017). "Third, we assessed whether loss of BAP1 and PBRM1 expression in metastatic tumors is associated with cancer-specific outcome." (PMID 28327121, 2017). "Eckel-Passow and colleagues analyzed the immunohistochemical expression of BAP1 and PBRM1 in primary and metastatic tumors from 97 patients." (PMID 34885018, 2021). "BAP1 and PBRM1 staining was performed on longitudinal metastatic tumors for 32 patients (median = 2, max = 4 metastatic tumors per patient)." (PMID 28327121, 2017). "Related to this, Gerlinger and colleagues compared mutations from patient-matched primary and metastatic tumors in four patients; all four were BAP1 wild type and two had PBRM1 mutations." (PMID 28327121, 2017). "Replicate blocks were analyzed for BAP1 and PBRM1 expression in 12 metastatic tumors in order to investigate intra-tumor heterogeneity (median = 2, max = 5 replicate blocks per metastatic tumor)." (PMID 28327121, 2017). "For the 97 patients with staining of PBRM1 in the primary tumor, we analyzed a total of 138 patient-matched metastatic tumors." (PMID 28327121, 2017). "Comparing expression across patient-matched primary-metastatic tumor pairs, the authors reported that 98% had concordant BAP1 status (90% PBRM1)." (PMID 34885018, 2021). "Comparing expression across patient-matched primary-metastatic tumor pairs, 98 and 90% had concordant BAP1 and PBRM1 expression, respectively." (PMID 28327121, 2017). "Amongst 32 patients who had serial metastatic tumors available, both BAP1 and PBRM1 had 97% concordant expression." (PMID 28327121, 2017). "We evaluated intra-metastatic tumor heterogeneity using 12 patients who had multiple blocks available from the same tumor with representative pathology; 100 and 92% showed concordant BAP1 and PBRM1 expression, respectively." (PMID 28327121, 2017).
pancreatic adenocarcinoma (3 papers, 2022 to 2025). "The genomic analysis showed the presence of a truncating mutation in PBRM1 in the pancreatic adenocarcinoma." (PMID 36056133, 2022). "An inquiry into the Cancer Genome Atlas-Pancreatic Adenocarcinoma (TCGA-PAAD) cohort for mutations and Genomic Identification of Significant Targets in Cancer (GISTIC) putative copy number alterations (CNAs) revealed frequent heterozygous loss of PBRM1." (PMID 40454484, 2025).
peritoneal mesothelioma (3 papers, 2020 to 2023). A benign or malignant mesothelial neoplasm that arises from the peritoneum. "In pleural and peritoneal mesothelioma, deletions in the 3p21 region, where PBRM1 is located, were frequently detected." (PMID 36138075, 2022). "Furthermore, in the peritoneal mesothelioma cohort in the previously cited study, the most common alterations detected in peritoneal mesothelioma were inactivating mutations in BAP1 (47.9%), NF2 (26.5%), CDKN2A (25.9%), CDKN2B (19.5%) and PBRM1 (15.8%)." (PMID 38136262, 2023). "The five most frequently altered genes in pleural mesothelioma were CDKN2A (48.2%), BAP1 (45.0%), CDKN2B (42.2%), NF2 (32.8%) and MTAP (32.3%), in peritoneal mesothelioma BAP1 (47.9%), NF2 (26.5%), CDKN2A (25.9%), CDKN2B (19.5%), PBRM1 (15.8%)." (PMID 36138075, 2022).
urothelial carcinoma (3 papers, 2020 to 2024). A malignant neoplasm derived from the transitional epithelium of the urinary tract (urinary bladder, ureter, urethra, or renal pelvis). "Next, n = 116 samples of patients with pure squamous cell carcinoma (n = 68) and mixed urothelial carcinoma with substantial squamous differentiation (n = 48) were analyzed for seven SWI/SNF complex proteins (ARID1A, SMARCA4, SMARCB1, SMARCC1, SMARCC2, SMARCA2 and PBRM1) by immunohistochemistry." (PMID 33227989, 2020).
uterine corpus endometrial carcinoma (3 papers, 2017 to 2023). A endometrial carcinoma (disease) that involves the body of uterus. "According to the TCGA pan-cancer cohort, PBRM1 mutation frequency was 5%, with the most prevalent in ccRCC (29.9%), followed by uterine corpus endometrial carcinoma (UCEC) (13.8%) and SKCM (9.3%)." (PMID 36699446, 2022).
Cowden syndrome (2 papers, 2019 to 2024). "Two different putative RCC-genes include PTEN known for its involvement in Cowden syndrome, in which patients have a genetic predisposition to RCC, and PBRM1 in which a heterozygote germline variant was found to segregate with RCC in four affected family members in a French RCC-family." (PMID 31034483, 2019).
epithelioid sarcoma (2 papers, 2021 to 2022). An aggressive malignant neoplasm of uncertain differentiation, characterized by the presence of epithelioid cells forming nodular patterns. "In particular, the SWI/SNF subunit SMARCB1 has been approved as an effective marker of metastatic or locally advanced epithelioid sarcoma sensitivity to tazemetostat, while SMARCA2, SMARCA4, ARID1A, and PBRM1 are potential marker candidates." (PMID 34202528, 2021).
gastric adenocarcinoma (2 papers, 2022 to 2023). "This article will explore the clinicopathological and molecular changes and tumor immune activity of the abnormal SWI/SNF complex subunit PBRM1 in gastric adenocarcinoma (GAC) and its significance." (PMID 35928964, 2022).
malignant rhabdoid tumors (2 papers, 2018 to 2021). "The authors suggest that immune checkpoint inhibition can be a potential therapeutic strategy in PBRM1-low rhabdoid tumors." (PMID 34830753, 2021). "PBRM1, which encodes a component of the PBAF complex, regulates the expression of immune-related genes, like interleukins (e.g., IL-13 and IL-16) and tumor necrosis factor alpha, in rhabdoid tumors." (PMID 34830753, 2021).
mental disorder (2 papers, 2018 to 2020). A disease that has its basis in the disruption of mental process. "Four eGenes (i.e., AS3MT, FLOT1, HLA-A, and PBRM1) are affected by eQTLs from all tested phenotypes and are current therapeutic targets for psychiatric disorders." (PMID 33192679, 2020). "For example, for two mental disorder-related functional SNPs near genes PBRM1 and ITIH1 in the GWAS Catalog, PheWAS suggested they might be associated with lipoma." (PMID 29378629, 2018).
mesothelioma (2 papers, 2017 to 2018). A usually malignant and aggressive neoplasm of the mesothelium which is often associated with exposure to asbestos. "High-coverage multi-gene studies can not only confirm key molecular events described in single-gene studies, but also uncover less common features that may be driving mesothelioma development, such as the loss of tumor suppressor genes SETD2, PBRM1, and PTEN." (PMID 30060501, 2018). "Moreover, silencing of SETD2 or PBRM1 was found to increase proliferation in a mesothelioma cell line." (PMID 29371938, 2017). "The results revealed biallelic gene inactivation of SETD2, BAP1, PBRM1, and SMARCC1, suggesting that the mesothelioma genome is affected by minute deletions that are non-detectable by singular NGS-based approaches or commercial array CGH." (PMID 30060501, 2018).
migraine (2 papers, 2021 to 2025). "The women-specific (GERA + UKB) meta-analysis (22,500 migraine cases and 279,762 controls) identified 19 loci (P < 5.0 × 10−8), of which three, CPS1 on chromosome 2, PBRM1 on chromosome 3, and SLC25A21 on chromosome 14, were additional novel loci." (PMID 34294844, 2021). "CPS1 rs1047891, PBRM1 rs11718509, and SLC25A21 rs10150336 were significantly associated with migraine in women (P < 5.0 × 10−8) but not in men (P > 0.05)." (PMID 34294844, 2021).
osteosarcoma (2 papers, 2019 to 2023). A usually aggressive malignant bone-forming mesenchymal neoplasm, predominantly affecting adolescents and young adults. "In contrast to the BAP1 mutation, PBRM1 mutation was primarily associated with ATAC-peaks exhibiting increased accessibility, suggesting PBRM1 may have a role in gene silencing, consistent with a previous report using osteosarcoma cells." (PMID 36973268, 2023).
pancreatic ductal adenocarcinoma (2 papers, 2025). An infiltrating adenocarcinoma that arises from the epithelial cells of the pancreas. "In this issue of the JCI, Kawai and colleagues leveraged genetically engineered mouse models (GEMM) of pancreatic ductal adenocarcinoma (PDAC) to demonstrate that loss of Pbrm1, a member of the SWI/SNF complex, drives dedifferentiation and aggressive tumor features." (PMID 40454477, 2025). "Polybromo 1 (PBRM1) is a tumor suppressor that controls tumor grade and metastasis of pancreatic ductal adenocarcinoma by regulating vimentin expression." (PMID 40454484, 2025). "Mutations in Polybromo 1 (PBRM1), a subunit of the switch/sucrose nonfermentable (SWI/SNF) chromatin remodeling complex, are frequently observed in several cancers, including pancreatic ductal adenocarcinoma (PDAC)." (PMID 40454484, 2025).
rhabdomyosarcoma (2 papers, 2025). A rare aggressive malignant mesenchymal neoplasm arising from skeletal muscle. "It has been reported that in ccRCC, PBRM1 promotes increased chromosome accessibility by regulating nucleosome dissociation 22, whereas in rhabdomyosarcoma, PBRM1 mutation may regulate cytotoxic T-cell infiltration by modulating aberrant chromosomal methylation." (PMID 40093909, 2025). "Another study of rhabdomyosarcoma 21 reported that PBRM1 knockdown decreased immunosuppressive cytokine secretion." (PMID 40093909, 2025).
skin cancer (2 papers, 2020 to 2023). "Thus, the P1225S mutation in certain skin cancers (COSMIC) could promote oncogenic development by disrupting PBRM1/PBAF-dependent histone binding, a conjecture that requires investigation." (PMID 37394010, 2023).
squamous cell carcinoma (2 papers, 2020 to 2025). A carcinoma arising from squamous epithelial cells. "Ten out of 12 samples of human pancreatic adenosquamous carcinoma or squamous cell carcinoma lost the PBRM1 expression." (PMID 40454484, 2025).
triple-negative breast carcinoma (2 papers, 2021 to 2023). An invasive breast carcinoma which is negative for expression of estrogen receptor (ER), progesterone receptor (PR), and human epidermal growth factor receptor 2 (HER2). "Here, we report that MUC1-C is necessary for PBRM1 expression and that it forms a nuclear complex with PBRM1 in triple-negative breast cancer (TNBC) cells." (PMID 36445328, 2023).
undifferentiated carcinoma (2 papers, 2021 to 2025). A usually aggressive malignant epithelial neoplasm composed of atypical cells which do not display evidence of glandular, squamous, or transitional cell differentiation. "We observed that pancreas-specific PBRM1 loss significantly accelerated the formation of poorly differentiated and undifferentiated carcinoma and increased distant metastasis with a worse prognosis." (PMID 40454484, 2025). "Some Pbrm1-deleted PDAC cells exhibited a transient state of degradation of the tubular component to a component of undifferentiated carcinoma with high vimentin expression and loss of expression of PBRM1 and CK19." (PMID 40454484, 2025). "This is the first reported case of an undifferentiated carcinoma with rhabdoid features in the gallbladder carrying a POLE mutation and SWI/SNF-deficiency of PBRM1 and SMARCA2." (PMID 34118935, 2021).
viral infection (2 papers, 2013 to 2025). "PBRM1 is a chromatin modulator of the SWI/SNF chromatin remodeling complex, which includes SMARCA4, SMARCB1, SMARCC1, ARID1A, DPF2, and SMARCE1, also implicated in ACE2 expression regulation and, thus, in host cell susceptibility to viral infection." (PMID 40378209, 2025). "Gene ontology classes of the predicted cellular targets of HPV16-miR-H1-1 suggest important roles in host cell interactions of HPV 16, such as the cell cycle process (CUL3, CYP26B1, MAP3K11, PBRM1, SMC1A), especially the M phase (CYP26B1, PBRM1, SMC1A), which is important for viral infection." (PMID 23936163, 2013).
adenoma (1 paper, 2015). A neoplasm arising from the epithelium. "In addition, frequent mutations in epigenetic modifiers (truncating mutations in ARID1A, MLL3, and PBRM1) were observed as clonal or adenoma-specific events." (PMID 26336987, 2015).